DCLK1 (doublecortin like kinase 1)
Diseases named in the same sentence as DCLK1 in open-access papers (continued):
Sharing a sentence is not in itself a finding about the gene and the disease.
Cirrhosis (7 papers, 2013 to 2024). A chronic disorder of the liver in which liver tissue becomes scarred and is partially replaced by regenerative nodules and fibrotic tissue resulting in loss of liver function. "Their findings suggest that the detection of elevated plasma DCLK1 may provide a potential companion diagnostic marker for patients with cirrhosis and HCC." (PMID 27610139, 2016). "This led us to investigate the correlation between DCLK1 and stage-specific transformation from liver fibrosis, cirrhosis, and HCC in patients, when compared with normal healthy subjects." (PMID 38928187, 2024). "miR-184, described as both an oncogene and tumor suppressor, was upregulated in a DCLK1-dependent manner during the progression from cirrhosis to HCC." (PMID 38928187, 2024). "Given that DCLK1 is upregulated in fibrosis, cirrhosis, and HCC, we examined if any previously identified DE miRNAs correlated with DCLK1 serum protein levels." (PMID 38928187, 2024). "This study focused on the role of the tumor stem cell protein doublecortin-like kinase 1 (DCLK1) in the modulation of molecular factors in fibrosis, cirrhosis, or HCC." (PMID 38928187, 2024). "We previously reported a mechanistic association between HCV infection and stemness in liver-derived cells and observed a marked increase in immunoreactive DCLK1 expression in HCV patients with cirrhosis." (PMID 38928187, 2024). "This suggests that high DCLK1 reduces miR-206, releasing signals that would otherwise prevent progression from cirrhosis to HCC." (PMID 38928187, 2024). "Consistent with an oncogenic role, we found miR-184 upregulated in a DCLK1-dependent manner in the progression from cirrhosis to HCC." (PMID 38928187, 2024). "We aimed to identify the unique DCLK1-specific downstream signaling pathways that indicate differences from cirrhosis to HCC." (PMID 38928187, 2024). "Our study found increased serum DCLK1 levels in patients with fibrosis, cirrhosis, and HCC compared with controls." (PMID 38928187, 2024). "The activation of S100A9/NF-κB pathway in hepatitis C virus via DCLK1 induces cirrhosis, and DCLK1 overexpression is positively correlated with the expression of inflammatory genes." (PMID 36369000, 2022). "Another study also supported the involvement of DCLK1 in activating NF-κB pathway to induce cirrhosis in hepatitis C virus." (PMID 36369000, 2022). "The activation of S100A9/NF-κB pathway in hepatitis C virus through DCLK1 induced cirrhosis, and DCLK1 overexpression was positively correlated with the expression of inflammatory genes." (PMID 36369000, 2022). "Next, we determined relative expression of DCLK1, and active and total β-catenin in the total lysates prepared from liver tissues of patients with cirrhosis and HCC." (PMID 32601309, 2020). "DCLK1-led activation of the atypical β-catenin signaling was also validated in a humanized liver mouse model and liver tissues of patients with cirrhosis and HCC." (PMID 32601309, 2020). "Here, we demonstrated increased DCLK1 expression in the epithelial and stromal compartments of tissues with cirrhosis and HCC." (PMID 26468984, 2015). "Here, we report the DCLK1's inflammatory and tumorigenic role in hepatitis B/C-induced cirrhosis and HCC." (PMID 25948779, 2015). "The level of DCLK1 protein and the numbers of DCLK1-positive cells are markedly increased in chronic HCV-infected patients with evidence of cirrhosis and hepatic nodules." (PMID 24260365, 2013). "We hypothesized that specific miRNAs regulated by DCLK1 would serve as key factors in the progression from fibrosis to cirrhosis and HCC." (PMID 38928187, 2024). "Thus, fibrosis and cirrhosis are best identified by an elevated DCLK1/TGF-β axis, while HCC is better distinguished via AFP-L3 and ACE2." (PMID 38928187, 2024). "However, there is a marked increase in hepatic DCLK1 expression after liver injury, cirrhosis, and HCC." (PMID 32601309, 2020).
Cirrhosis (continued). "To determine whether active β-catenin and DCLK1 are expressed in the same liver cells, we performed co-immunohistochemical staining of liver tissues from patients with cirrhosis and HCC (n = 20)." (PMID 32601309, 2020). "Interestingly, increased DCLK1 expression correlated with S100A9 for the most cell-types in HCV-positive cirrhosis." (PMID 25948779, 2015). "Nevertheless, DCLK1 expression in cirrhosis may open the doors to evaluating other functional stem cell proteins." (PMID 26468984, 2015). "We are the first to demonstrate detectable DCLK1 in the plasma of patients with cirrhosis and HCC." (PMID 26468984, 2015). "Moreover, we separately reported that DCLK1 is upregulated in cirrhosis and HCC and suggested that the mechanism may be miRNA-mediated." (PMID 38928187, 2024). "In contrast with increased DCLK1 in all three conditions, we found that its downstream effector, TGF-β, was only upregulated in fibrosis and cirrhosis." (PMID 38928187, 2024). "We observed elevated serum DCLK1 levels in fibrosis, cirrhosis, and HCC patients; however, TGF-β levels were only elevated in fibrosis and cirrhosis." (PMID 38928187, 2024). "Liver tissues from patients with cirrhosis and HCC revealed epithelial co-staining of DCLK1 and active β-catenin, and cleaved E-cadherin." (PMID 32601309, 2020). "A large percentage (60%-70%) of patients with cirrhosis and HCC express DCLK1 in their livers and this expression correlates with a worse prognosis." (PMID 32601309, 2020). "They further revealed that the high expression of DCLK1 also correlated with increased levels of S100A9, c-Myc, and BRM levels in HCV/HBV-positive patients with cirrhosis and HCC." (PMID 27610139, 2016). "The DCLK1 overexpression also correlates with increased levels of S100A9, c-Myc, and BRM levels in HCV/HBV-positive patients with cirrhosis and HCC." (PMID 25948779, 2015). "In contrast, epithelial and stromal cells, Kupffer cells, lymphocytes, and bile ducts showed expression of DCLK1 and S100A9 in cirrhosis." (PMID 25948779, 2015). "DCLK1 protein was detected in the plasma of all patients with HCC and in 80% of cirrhosis controls, consistent with our archived histopathology study, even though the studies were conducted with samples from different repositories." (PMID 26468984, 2015). "Unlike normal livers, which lack both DCLK1 and 80-kDa E-cadherin, livers from patients with cirrhosis and HCC clearly showed both proteins." (PMID 32601309, 2020). "Doublecortin-like kinase 1 (DCLK1), a tumor stem cell marker, is induced during cirrhosis and HCC." (PMID 32601309, 2020). "In the present study, we found increased expression of DCLK1 in plasma and epithelial and stromal compartments of tissues with cirrhosis and HCC compared with non-cirrhotic controls (NCCs)." (PMID 26468984, 2015). "This supports our hypothesis that DCLK1+ cells in HCC may undergo EMT and can be detected in the bloodstream as a biomarker for cirrhosis and HCC." (PMID 26468984, 2015). "Because chronic inflammation associated with HCV infection is considered a major contributor to cirrhosis and the development of HCC, the transcriptome data provided legitimate basis to investigate the relationship between DCLK1 and S100A9 in the context of HCV infection." (PMID 25948779, 2015). "Because the onset of cirrhosis and HCC occurs during chronic HCV infection, an increase in DCLK1 is not observed in an acute infection model." (PMID 25948779, 2015). "We immunostained tissues from human livers with HCC, cirrhosis controls (CC), and non-cirrhosis controls (NCC) for DCLK1." (PMID 26468984, 2015).
pancreatic adenocarcinoma (7 papers, 2014 to 2022). "For example, KDM3A upregulates the CSC marker DCLK1 by binding to the DCLK1 promoter in pancreatic adenocarcinoma." (PMID 36008383, 2022). "We have demonstrated that DCLK1 is stem cell marker whose expression is upregulated in both colon and pancreatic adenocarcinomas." (PMID 26673007, 2016). "We have demonstrated that doublecortin and CaM kinase-like-1 (DCLK1) is an intestinal stem cell marker that is expressed in colon adenocarcinoma and also in pancreatic adenocarcinoma." (PMID 26673007, 2016). "The aim of this study was to shed light on the role of inflammation in DclK-1-positive CSCs and pancreatic adenocarcinoma and to evaluate the pharmacologic effects of licofelone on PC." (PMID 25906749, 2015). "Notably, in pancreatic adenocarcinoma, overexpression of DCLK1 in tumor cells has been shown to educate M2 macrophages resulting in CD8+ T-cell suppression, whereas silencing DCLK1 has the reverse effect." (PMID 34830884, 2021). "LGR5 and BMI1 are stem-cell markers coexpressed with DCLK1 in the intestine, regulated downstream of DCLK1 following radiation injury in intestinal epithelial DCLK1 knockout mice, and markers of populations of cells with tumor stem cell activity in intestinal adenomas and pancreatic adenocarcinoma." (PMID 24885928, 2014). "Prospective isolation and molecular and biological characterisation of subpopulations of putative progenitor cells in pancreatic adenocarcinomas will be required to obtain a better understanding of the relationship between progenitor populations marked by GCTM-5, SOX9, LGR5, and DCLK1." (PMID 30814526, 2019).
intestinal cancer (6 papers, 2014 to 2022). "The tumorigenic properties of Dclk1-marked intestinal cancer stem cells have been proven in ApcMin/+, suggesting their role in CRC." (PMID 27388564, 2016). "Therefore, it is speculated that DCLK1-positive tuft lineage cells are multipotent, or at least bipotent, ectopically transforming into NET cells and orthotopically into intestinal cancer cells, under specific microenvironmental conditions." (PMID 26622789, 2015). "Our data shows that ablation of Dclk1 expression results in the regression of polyps and dysplasia without injury to the normal intestine, suggesting that Dclk1 maybe a potential therapeutic target in intestinal cancer." (PMID 25211188, 2014).
schizophrenia (6 papers, 2012 to 2022). A major psychotic disorder characterized by abnormalities in the perception or expression of reality. "The drug-regulated isoform contains genetic variants of DCLK1 that have been previously associated with schizophrenia and hyperactivity disorder in humans." (PMID 30208879, 2018). "We investigated the role of DCLK1 variants in three psychiatric disorders that have neuro-cognitive dysfunctions: schizophrenia (SCZ), bipolar affective disorder (BP) and attention deficit/hyperactivity disorder (ADHD)." (PMID 22539971, 2012). "Polymorphisms in the Dclk1 gene are associated with the development of schizophrenia." (PMID 30208879, 2018). "This enabled us to reveal the significance of the SNARE complex in synaptic abnormalities and indicated a schizophrenia candidate gene DCLK1 believed to be involved in neuronal development." (PMID 22558445, 2012).
clear cell renal cell carcinoma (5 papers, 2015 to 2025). "Herein, we reveal that DCLK1 is significantly activated, with a concomitant alternative-promoter model switch (β-to-α) towards the long variants (isoform 1 and 2) in clear cell renal cell carcinoma (ccRCC)." (PMID 40775208, 2025).
esophageal cancer (5 papers, 2020 to 2025). A primary or metastatic malignant neoplasm involving the esophagus. "As a well-recognized marker for CSCs in colon, pancreatic, gastrointestinal, breast, and esophageal cancers, DCLK1 is linked to more aggressive tumor types and treatment resistance." (PMID 39781521, 2025). "In esophageal cancer-related studies, DCLK1 promotes EMT phenotype transformation through the MAPK/ERK/MMP2 pathway." (PMID 37239162, 2023). "To date, DCLK1 has been demonstrated to be a relatively selective marker of several kinds of cancer stem-like cells or cancer stem cells (CSCs) including in colon, breast, pancreas, kidney, and esophageal cancers." (PMID 33348546, 2020).
non-small cell lung carcinoma (5 papers, 2020 to 2022). A group of at least three distinct histological types of lung cancer, including non-small cell squamous cell carcinoma, adenocarcinoma, and large cell carcinoma. "DCLK1 (+ 60.2-fold) has been reported to be associated with chemoresistance to cisplatin in non-small cell lung cancer cells and targeting DCLK1 by miR539 led to increased sensitivity to cisplatin." (PMID 33515271, 2021). "However, the expression and biological function of DCLK1 in non-small cell lung carcinoma (NSCLC) remain unclear." (PMID 33762936, 2021). "The Cancer Genome Atlas (TCGA) database revealed elevated DCLK1 in lung squamous cell adenocarcinoma (LUAD), indicating that it is an implicit target in non-small cell lung cancer (NSCLC)." (PMID 36250024, 2022). "In non-small cell lung carcinoma (NSCLC) cells, XMD-17-51 inhibited DCLK1 and cell proliferation, while DCLK1 overexpression impaired the anti-proliferative activity of XMD-17-51 in A549 cell lines." (PMID 33762936, 2021).
influenza (4 papers, 2020 to 2024). An acute viral infection of the respiratory tract, occurring in isolated cases, in epidemics, or in pandemics; it is caused by serologically different strains of viruses (influenzaviruses) designated A, B, and C, has a 3-day incubation period, and usually lasts for 3 to 10 days. "Another potential role of DCLK1 is associated with lung regeneration, as previous studies have shown an increased expression of DCLK1-positive cells during dysplastic lung repair in influenza and bleomycin-induced lung injury." (PMID 37996782, 2023). "After influenza infection, DCLK1+TRPM5+ SCCs coexpress p63 and arise near Krt5+ cells, suggesting a common origin with p63+Krt5+ distal airway epithelial cells implicated in lung regeneration." (PMID 38061015, 2024). "In mice, DCLK1+ chemosensory cells develop in the distal lung after severe influenza injury." (PMID 38061015, 2024). "DCLK1+TRPM5+ SCCs develop in the distal lung after severe influenza injury." (PMID 38061015, 2024). "DCLK1+ chemosensory cells develop in the distal lung after severe influenza injury." (PMID 38061015, 2024). "(A–B, D–E) Lung sections stained for Krt5 in green, Dclk1 in red, DAPI in blue 22 days after influenza infection." (PMID 36073526, 2022). "(A–P) Lung sections stained for Krt5 in green, Dclk1 in red, and DAPI in blue 22–25 days after influenza." (PMID 36073526, 2022).
ovarian carcinoma (4 papers, 2019 to 2026). A malignant neoplasm originating from the surface ovarian epithelium. "In ovarian clear cell carcinoma, a subtype of epithelial ovarian cancer associated with poor prognosis and chemoresistance, miR-424 targets doublecortin-like kinase 1 (DCLK1) which is associated with cancer stem cells in multiple cancers." (PMID 30474694, 2019). "DCLK1 expression was analyzed across patient-derived ascites cultures established from primary and recurrent ovarian cancer patients and correlated with markers of metastasis-initiating cells." (PMID 42210222, 2026). "Targeting DCLK1 or downstream IL-6/JAK-STAT signaling may therefore offer a rational strategy to disrupt metastatic dissemination in ovarian cancer." (PMID 42210222, 2026). "Although this aligns with prior research in other solid tumors; for instance, increased DCLK1 has been reported to induce pancreatic, colorectal and ovarian cancer cell migration and invasion, the mechanisms through which DCLK1 exerts these effects in HNSCC remain largely unknown." (PMID 34336664, 2021). "In ovarian cancer, miR-424 can act as a tumor suppressor by inhibiting cell migration, invasion, and EMT via down-regulating the expression of doublecortin-like kinase 1 (DCLK1) and MYB." (PMID 36969009, 2023).
prostate carcinoma (4 papers, 2011 to 2025). A carcinoma that arises from epithelial cells of the prostate gland. "In concordance with previous reports describing absence of DCLK1 in human tuft cells, we do not observe DCLK1 in COX1+ tuft-like cells in human prostate cancer." (PMID 37386128, 2023). "In human prostate cancers, tuft-like cells express COX1, active EGFR and active SFKs, but not DCLK1 and COX2." (PMID 37386128, 2023). "We performed immunofluorescent staining of a prostate cancer TMA, containing both non-malignant and cancer cores, and observed two distinct expression patterns of DCLK1 staining, including cytoplasmic/membrane staining of whole glands, and single cell staining." (PMID 37386128, 2023).
renal carcinoma (4 papers, 2019 to 2023). A carcinoma arising from the epithelium of the renal parenchyma or the renal pelvis. "DCLK1 has been shown to regulate epithelial-to-mesenchymal transition as well as serving as a cancer stem cell marker in colon, pancreatic and renal cancer." (PMID 34336664, 2021). "Herein, we comprehensively review the mechanistic role of DCLK1 in the tumor microenvironment, assess the potential for targeting DCLK1 in colon, pancreatic and renal cancer." (PMID 33348546, 2020). "We recently reported that monoclonal antibody CBT-15 targeting DCLK1-AL/BL inhibits renal cancer tumorigenesis in vivo." (PMID 31467540, 2019).
atherosclerosis (3 papers, 2021 to 2024). A disease characterized by the build-up of fatty material and calcium deposition in the arterial wall resulting in partial or complete occlusion of the arterial lumen. "Macrophage DCLK1 promotes inflammatory atherosclerosis by directly binding to IKKβ and activating IKKβ/NF‐κB signal." (PMID 36896602, 2023). "In this study, we identified upregulated DCLK1 in macrophages in atherosclerotic lesions of ApoE−/− mice fed an HFD and determined that macrophage‐specific DCLK1 deletion attenuates atherosclerosis by reducing inflammation in mice." (PMID 36896602, 2023). "This elevated expression of DCLK1 in macrophages mediated oxLDL‐induced inflammatory responses, which subsequently promotes the pathogenesis of atherosclerosis." (PMID 36896602, 2023). "This study reports DCLK1 as a new IKKβ regulator in inflammation and a potential therapeutic target for inflammatory atherosclerosis." (PMID 36896602, 2023). "In this study, we evaluated the role of DCLK1 in atherosclerosis both in vivo and in vitro." (PMID 36896602, 2023). "DCLK1 is a new regulator of IKKβ and a potential therapeutic target for atherosclerosis." (PMID 36896602, 2023). "Collectively, we have identified DCLK1 as a novel inflammatory regulator in atherosclerosis." (PMID 36896602, 2023). "To determine whether DCLK1 is involved in atherosclerosis, we first examined the levels of DCLK1 in experimental atherosclerotic mouse models using publicly available transcriptome data." (PMID 36896602, 2023). "Then, we investigated the role of DCLK1 in high‐fat diet‐induced atherosclerosis." (PMID 36896602, 2023). "Thus, this is the first time to identify a new function of DCLK1 in inflammatory atherosclerosis and show that DCLK1 mediates oxLDL‐induced inflammation in macrophages." (PMID 36896602, 2023). "However, the role of DCLK1 in atherosclerosis remains undefined." (PMID 36896602, 2023). "Whether the rest of them, including Dkk2, Ltbp2, Lamb1, Cdca7l, Dclk1, and Slc45a4, are associated with atherosclerosis and d-flow has not been reported." (PMID 34282126, 2021). "DCLK1, EGFR, and MTOR (all connected to the ATP binding pathway) have been identified as potential therapeutic targets for atherosclerosis." (PMID 39796045, 2024). "The role of DCLK1 in atherosclerosis and cardiovascular diseases has not been studied yet." (PMID 36896602, 2023).
attention deficit-hyperactivity disorder (3 papers, 2012 to 2023). A disorder characterized by a marked pattern of inattention and/or hyperactivity-impulsivity that is inconsistent with developmental level and clearly interferes with functioning in at least two settings (e.g. at home and at school). "In contrast, DCLK1 mutations and overexpression have been associated with neurodevelopmental and neuropsychiatric disorders, including attention deficit hyperactivity disorder (ADHD), schizophrenia and bipolar disorder." (PMID 36979969, 2023).